AJUBA (ajuba LIM protein)
Diseases named in the same sentence as AJUBA in open-access papers (continued):
Sharing a sentence is not in itself a finding about the gene and the disease.
tumor (26 papers, 2016 to 2026). "In the current study, immunohistochemistry (IHC) showed that expression of AJUBA was upregulated in 67.55% of NSCLC tumor samples and was associated with tumor size, lymph node metastasis, advanced tumor stage, poor differentiation and poor prognosis." (PMID 40240814, 2025). "AJUBA activity has been linked to a variety of cancers, and intriguingly has been found to act in some cases as a tumor suppressor, and in other cases as an oncogene." (PMID 36439396, 2022). "A focal, heterozygous deletion affected AJUBA in one tumor, and in the same tumor there was a point mutation affecting the other allele." (PMID 34272401, 2021). "WNT signaling activation in HN tumor subsites has been associated with genetic alterations in AJUBA, FAT1 and NOTCH1." (PMID 34208581, 2021). "In this cohort, expression level of AJUBA was associated with tumor cell differentiation (P = 0.043, χ2 test) and invasion depth (T stage, P = 0.005, Fisher's exact test)." (PMID 27172796, 2016). "Furthermore, loss of AJUBA expression decreased tumor burden in a murine model of colorectal metastasis to the liver." (PMID 37765273, 2023). "In vivo, AJUBA knockdown led to suppressed tumor growth, reduced Ki-67 proliferation indices, and diminished M2 macrophage abundance." (PMID 41814682, 2026). "Taken together, these data indicate that AJUBA promoted tumor growth via regulation of the ERK and Wnt/β-catenin pathway in NSCLC." (PMID 40240814, 2025). "AJUBA has been confirmed to be a target gene of certain microRNAs that have tumor-suppressing effects." (PMID 40240814, 2025). "AJUBA has functioned as an oncogene in most studies, but also has been shown to have tumor-suppressing effects in certain cancers." (PMID 40240814, 2025). "Silencing of AJUBA repressed tumor growth and led to a decrease in p-ERK, β-catenin and N-cadherin in vivo." (PMID 40240814, 2025). "The high expression of AJUBA is related to tumor epithelial–mesenchymal transition (EMT), migration, and metastasis and patient survival." (PMID 35898403, 2022). "In particular, these genes are associated with more aggressive tumor phenotype (SAL2), migration and invasion (TOX4, PRMT5, AJUBA) development and progression (ZNF219, CEBPE)." (PMID 34944989, 2021). "These mutations result in protein products that lack the LIM domain, indicating that they are loss-of-function mutations: since mutated AJUBA seems to promote ESCC carcinogenesis, these data suggest that AJUBA has a tumor suppressive role in ESCC." (PMID 32759723, 2020). "Ajuba LIM protein (JUB, also called AJUBA) is a well-known cancer associated protein, which is involved in tumor invasion and migration." (PMID 29596435, 2018). "From 179 paired samples, we found that AJUBA was significantly overexpressed in tumor tissues than in adjacent non-tumor tissues (mean, 2.15-fold; P < 0.001, paired Student's t-test, two-tailed)." (PMID 27172796, 2016). "KLF6 isoforms were also found to be involved in tumor progression, and the activity of AJUBA was found to promote cancer growth." (PMID 27902686, 2016). "In line with these clinical data, AJUBA knockdown effectively inhibited cell growth, colony formation, and tumor formation." (PMID 27172796, 2016). "When we conducted the AJUBA upregulation experiment with the addition of an ERK inhibitor, we found that the experimental dose of the ERK inhibitor did not completely offset the protein upregulation and enhanced tumor malignancy caused by AJUBA upregulation." (PMID 40240814, 2025). "Meanwhile, the experimental results suggested that AJUBA may also regulate tumor malignancy through ERK-independent pathways, which needs to be confirmed in future studies." (PMID 40240814, 2025).
tumor (continued). "In conclusion, our study revealed that AJUBA was frequently upregulated in ESCC tumor tissues." (PMID 27172796, 2016). "In addition, AJUBA mRNA levels were significantly associated with elevated MMP10 and MMP13 expression in 179 ESCC tumor tissues (r = 0.441, P < 0.001 and r = 0.404, P < 0.001, respectively), suggesting that AJUBA promotes the expression of MMP10 and MMP13 in ESCC." (PMID 27172796, 2016). "The phosphorylated variant of SNAIL, in complex with HDAC1 and HDAC2, exhibits stability in the nuclear environment and promotes the upregulation of tumor proliferation markers, including CYCLIN D1 and the Ajuba LIM protein (AJUBA)." (PMID 41250755, 2025). "Notably, in some cases oncogenic activity of AJUBA has been correlated with increased YAP activity, whereas tumor suppressor activity of AJUBA has been correlated with decreased YAP activity." (PMID 36439396, 2022). "In the present study, we detected AJUBA levels in ESCC tumor tissues and in corresponding adjacent non-tumor tissues by immunohistochemistry (IHC) and investigated the function and mechanism of AJUBA in ESCC cells." (PMID 27172796, 2016). "Interestingly, we found that AJUBA showed a 3‐fold up‐regulation in tumour tissues compared with adjacent healthy tissues and a negative correlation with the expression of miR‐1184 in tumour tissues." (PMID 32681581, 2020). "Here, we analyzed the mRNA levels of AJUBA and two other AJUBA family members, WTIP and LIMD1, in ESCC tumor tissues and in their matched adjacent non-tumor tissues." (PMID 27172796, 2016).
cancer (23 papers, 2016 to 2025). A tumor composed of atypical neoplastic, often pleomorphic cells that invade other tissues. "Taken together, the results of this pan-cancer analysis revealed that the abnormal expression of AJUBA relates with clinical prognosis, gene mutation, protein phosphorylation, and immune cell infiltration in various cancer types." (PMID 35898403, 2022). "The AJUBA protein has been implicated in the development of several human cancers." (PMID 37765273, 2023). "Accumulating evidence indicates that AJUBA acts as a potential target for new therapeutics to treat cancers." (PMID 40240814, 2025). "AJUBA overexpression reduced the sensitivity of cancer cells to chemotherapeutic drugs and vice versa." (PMID 36931700, 2023). "We made use of the CPTAC database to explore the phosphorylation of AJUBA between cancer tissues and normal tissues." (PMID 35898403, 2022). "The results reveal that the AJUBA gene is considered as a potential clinical biomarker for the prognosis of cancer patients, especially in LIHC, ESCA, and PAAD." (PMID 35898403, 2022). "Taken together, these results reveal that aberrant AJUBA expression is associated with the TME and EMT to promote angiogenesis, invasion, and metastasis in various cancer types." (PMID 35898403, 2022). "Previous studies have shown that the different molecular mechanisms of AJUBA promote tumorigenesis and development in a variety of cancers." (PMID 35898403, 2022). "According to the TCGA, HPA cohort, and GEPIA datasets, the gene expression analysis demonstrated that aberrant expression of AJUBA occurred usually across a variety of cancer types." (PMID 35898403, 2022). "A number of gene nodes linked to drug resistance in other cancer types (including CAT, TRIM59, ANXA2, ADM, AJUBA, HSPA1A/1B, LAMC2, TRIM14, KRT8, KRT18, KRT9, CLDN1, and SMARCA2) were also down-regulated in PARPis-sensitive AsPCs." (PMID 33213473, 2020). "In addition, abnormal expression levels of AJUBA are correlated with poor prognosis among many human cancer types, which vigorously reveals that AJUBA is a potential prognostic biomarker in cancer patients." (PMID 35898403, 2022). "This relationship between AJUBA expression and CAFs might be another reason for the poor prognosis and metastasis of AJUBA in various type of cancers." (PMID 35898403, 2022). "On the other hand, as the Hippo pathway is also an autoinhibitory pathway, the control of Hippo pathway activity depends on several internal inhibitors, such as FATs and AJUBA, and the functional MST-LATS-YAP/TAZ cascade, while abnormalities in Hippo signaling can be linked to several human cancers." (PMID 35820928, 2022). "However, previous studies have primarily focused on the Drosophila homolog of AJUBA, and the role of AJUBA in human cancer development has been controversially reported." (PMID 27172796, 2016). "Therefore, differential AJUBA gene expression in different cancers revealed that AJUBA may have diverse biological functions across various cancer types." (PMID 35898403, 2022). "However, the role of AJUBA in cancers remains to be elucidated." (PMID 32802179, 2020). "Our results revealed that the molecule MCULE-2386589557-0-6 interacts with AJUBA, leading to a misplaced interaction between AJUBA and CTNNB1, interfering in this pathway and probably preventing its role in cancer establishment." (PMID 37765273, 2023). "The concurrent activation of AJUBA and YAP protects cancer cells from DNA damage and promotes resistance to chemotherapy, as concluded by previous studies." (PMID 35885009, 2022). "We first analyzed the Cancer Cell Line Encyclopedia (CCLE) project data and found that AJUBA is expressed at a relatively high level in HCC cells among various types of human cancer cells." (PMID 32802179, 2020).
cancer (continued). "Besides, as a direct regulator of P-body formation, AJUBA is also phosphorylated by CDK1 and mitotic phosphorylation of AJUBA promotes cancer cell proliferation." (PMID 39046443, 2024).
digestive system tumors (1 paper, 2022). "Specifically, we further analyzed AJUBA expression in digestive system tumors (COAD, ESCA, LIHC, and STAD) (p < 0.001)." (PMID 35898403, 2022).
head and neck tumors (1 paper, 2020). "Genomic studies of head and neck tumors have shown that although β-catenin is not frequently mutated in HNSCC, its activity is not inhibited by mutations in upstream gene encoding β-catenin, NOTCH1, FAT1, and AJUBA." (PMID 33469547, 2020).
AJUBA also shares sentences with these, for which no sentence is quoted: cutaneous squamous cell carcinoma (2 papers); adenocarcinoma (1); breast invasive carcinoma (1); cervical squamous cell carcinoma (1); diffuse large B-cell lymphoma (1); endocervical adenocarcinoma (1); esophageal cancer (1); Fanconi anemia (1); lung adenocarcinoma (1); lung squamous cell carcinoma (1); lymphoid neoplasm (1); mastitis (1); metastatic prostate carcinoma (1); oesophageal cancer (1); oral cancers (1); ovarian carcinoma (1); ovarian serous cystadenocarcinoma (1); pancreatic adenocarcinoma (1); pancreatic ductal adenocarcinoma (1); pheochromocytoma (1); testicular germ cell tumor (1); uterine carcinosarcoma (1); xeroderma pigmentosum (1).